WARS2 (tryptophanyl tRNA synthetase 2, mitochondrial)
Description:
Catalyzes the attachment of tryptophan to tRNA(Trp) in a two-step reaction: tryptophan is first activated by ATP to form Trp-AMP and then transferred to the acceptor end of tRNA(Trp).
Synonyms: TrpRS; mtTrpRS; NEMMLAS; PKDYS3
Tractability: Small molecule: a structure with a bound ligand is known. Antibody: its Gene Ontology location is reachable by antibodies, with high confidence. PROTAC: ubiquitination databases record sites on it; its protein half-life has been measured.
Gene: Protein-coding gene on chromosome 1 (119,030,284 to 119,140,673, reverse strand). Ensembl gene ENSG00000116874.
Subcellular location: Mitochondrion matrix; Mitochondrion
Subcellular location (Human Protein Atlas): Mitochondria
Pathways (Reactome):
Metabolism of proteins: Mitochondrial tRNA aminoacylation
Gene Ontology:
Molecular function: tryptophan-tRNA ligase activity; aminoacyl-tRNA ligase activity; ATP binding; nucleotide binding
Biological process: mitochondrial tryptophanyl-tRNA aminoacylation; tRNA aminoacylation for protein translation; tryptophanyl-tRNA aminoacylation
Cellular component: mitochondrial matrix; mitochondrion
Genetic constraint (gnomAD): Loss-of-function variants: 28 observed, 34.96 expected, observed/expected ratio (o/e) 0.8, 90% interval 0.59 to 1.1. The upper end of that interval is the gene's LOEUF score, 1.1, which puts it in group 4 of 6, group 1 being the genes least tolerant of losing a copy. Missense variants: 427 observed, 466.16 expected, observed/expected ratio (o/e) 0.92, 90% interval 0.85 to 0.99. Synonymous variants: 171 observed, 184.12 expected, observed/expected ratio (o/e) 0.93, 90% interval 0.82 to 1.05.
Gene-disease validity (ClinGen):
ClinGen rates the evidence that WARS2 causes each of these diseases.
mitochondrial disease (autosomal recessive): Definitive.
Homologues: Orthologues: chimpanzee WARS2 (100% identical), macaque WARS2 (95% identical), pig WARS2 (89% identical), rabbit WARS2 (89% identical), mouse Wars2 (86% identical), guinea pig WARS2 (85% identical), rat Wars2 (82% identical), dog WARS2 (82% identical), tropical clawed frog wars2 (64% identical), zebrafish wars2 (61% identical), Drosophila melanogaster TrpRS-m (49% identical), Caenorhabditis elegans prx-10 (38% identical). Paralogues in human: WARS1 (18% identical).
Diseases named in the same sentence as WARS2 in open-access papers:
WARS2 is named in the same sentence as 48 diseases in open-access papers, as found by Europe PMC text mining. Sharing a sentence is not in itself a finding about the gene and the disease. The quoted sentences say what the papers report.
epilepsy (4 papers, 2019 to 2025). A brain disorder characterized by episodes of abnormally increased neuronal discharge resulting in transient episodes of sensory or motor neurological dysfunction, or psychic dysfunction. "The epilepsy phenotypes linked to WARS2 mutations encompass a spectrum of conditions, ranging from developmental and epileptic encephalopathies (DEE) observed in neonates or infants to less clearly defined seizure disorders." (PMID 39061374, 2024). "Deficiency of WARS2 was observed in a patient with severe infantile-onset leukoencephalopathy, profound intellectual disability, spastic quadriplegia, epilepsy and microcephaly." (PMID 36539902, 2022). "Furthermore, mutations in the WARS2 gene, responsible for encoding tryptophanyl-tRNA synthetase 2, have been correlated with a variety of neurological manifestations, such as epilepsy and motor deficits." (PMID 39061374, 2024).
Obesity (4 papers, 2020 to 2024). Accumulation of substantial excess body fat. "Eight prioritised regulatory SNPs in the TBX15/WARS2 region are risk candidates for obesity and/or osteoporosis risk." (PMID 37139670, 2023). "Several potential functional genes, including CHAF1A, CEP192, ULK4, CYP2D6, AS3MT, and WARS2, were identified as common genetic factors linking obesity and IS." (PMID 39734234, 2024). "The identification of CHAF1A, CEP192, ULK4, CYP2D6, AS3MT, and WARS2 as potential functional genes common to both obesity and IS enriched our understanding of their genetic interplay, potentially advanced our grasp of their pathogenesis and therapeutic targets." (PMID 39734234, 2024).
developmental delay (3 papers, 2018 to 2019). "Theisen et al8 reported an individual harboring different biallelic missense mutations in WARS2 who had developmental delay, infantile‐onset leukoencephalopathy, spasticity, hypotonia, tremor, muscle atrophy, and seizures." (PMID 29120065, 2018). "Mutations in the mitochondrial tryptophanyl‐tRNA synthetase, WARS2 (MIM 604733), have been linked to developmental delay, intellectual disability, microcephaly, seizures, and brain atrophy, but also with aggressive behavior hepatopathy, or early onset Parkinsonism." (PMID 30920170, 2019).
hearing loss (2 papers, 2016 to 2023). "Mutations in WARS2 have not been directly linked to hearing loss in human patients, however, sensorineural hearing loss is caused by mutations in other ARS2 genes." (PMID 37274208, 2023).
Parkinsonism (2 papers, 2018). Characteristic neurologic anomaly resulting from degeneration of dopamine-generating cells in the substantia nigra, a region of the midbrain, characterized clinically by shaking, rigidity, slowness of movement and difficulty with walking and gait. "The mutations in genes encoding cytoplasmic (WARS) and mitochondrial (WARS2) TrpRS enzymes cause the TrpRS deficiency, intellectual disability and Parkinsonism." (PMID 29587458, 2018). "This case expands the phenotypic spectrum of WARS2 deficiency and emphasizes the importance of mitochondrial protein synthesis in the pathogenesis of Parkinsonism." (PMID 29120065, 2018). "Here, we present a fourth patient with compound heterozygous mutations in WARS2 and a clinical presentation of infantile‐onset, Levodopa‐responsive Parkinsonism." (PMID 29120065, 2018). "The association of the patient's WARS2 variants to Parkinsonism or PD may be further clarified by systematically interrogating available cohorts for such mutations." (PMID 29120065, 2018).
acute liver failure (1 paper, 2018). Rapid deterioration of liver function causing encephalopathy and coagulopathy. "Apparently, pathogenic mutations in the nuclear genes POLG, TWNK and WARS2, and in the mitochondrial genes tRNALeu and tRNALys, all affecting intramitochondrial transcription and/or translation, have been associated with valproate-induced acute liver failure." (PMID 29783990, 2018).
autosomal recessive intellectual disability (1 paper, 2018). "Recently, the gene encoding mitochondrial tryptophanyl tRNA synthetase (WARS2) was reported to cause 2 different neurological phenotypes, a form of autosomal recessive intellectual disability and a syndrome of severe infantile‐onset leukoencephalopathy." (PMID 29120065, 2018).
cardiomyopathy (1 paper, 2023). A disease of the heart muscle or myocardium proper. "The clinical spectrum associated with WARS2 defects appears to be quite broad, including clinical features (cardiomyopathy, movement disorders, retinitis pigmentosa, optic atrophy, hypoglycemia, etc.)as well as the age of onset and clinical course." (PMID 37055858, 2023).
Dystonia (1 paper, 2025). An abnormally increased muscular tone that causes fixed abnormal postures. "Among the dystonic children, 9 were diagnosed with CP, 3 with pantothenate kinase-associated neurodegeneration (PKAN), 3 with KMT2B, 2 with SLC18A2-related dystonia, 2 with WARS2, and 2 with suspected neurotransmitter disorder." (PMID 40531829, 2025).
hepatocellular carcinoma (1 paper, 2025). A malignant tumor that arises from hepatocytes. "The latest study has unveiled a notable upregulation of WARS2 in hepatocellular carcinoma cells, indicating its potential as an immunotherapeutic target against liver cancer." (PMID 40360443, 2025).
hepatopathy (1 paper, 2018). "More observations are needed to confirm that WARS2 deficiency can be added to the list of mitochondrial defects associated with valproate-induced hepatopathy." (PMID 29783990, 2018). "In conclusion, we broaden the clinical spectrum of WARS2 deficiency and report for the first time a severe hepatopathy associated with valproate treatment in a subject with WARS2 deficiency." (PMID 29783990, 2018). "This is the first report of severe hepatopathy in a subject with WARS2 deficiency." (PMID 29783990, 2018).
hypertrophic cardiomyopathy (1 paper, 2018). A condition in which the myocardium is hypertrophied without an obvious cause. "We report here the identification of an ENU-induced mouse mutant harboring a recessive hypomorphic point mutation in the Wars2 gene, Wars2V117L, which causes a complex tissue-specific pathology, including hearing loss, reduced adiposity, adipose tissue dysfunction, and hypertrophic cardiomyopathy." (PMID 30566859, 2018). "We demonstrate that hypomorphic Wars2 alleles, Wars2V117L/− and Wars2V117L/V117L, which do not have direct genocopies in humans, cause sensorineural hearing loss, reduced adiposity, and hypertrophic cardiomyopathy in mice." (PMID 30566859, 2018).
liver failure (1 paper, 2018). A liver disease characterized by the liver losing or has lost all of its function. "No other WARS2 deficient subjects with severe liver failure were reported previously." (PMID 29783990, 2018).
lung adenocarcinoma (1 paper, 2025). A carcinoma that arises from the lung and is characterized by the presence of malignant glandular epithelial cells. "To delineate the cell-type-specific expression pattern and biological function of WARS2 in lung adenocarcinoma (LUAD), we performed single-cell RNA sequencing analysis across tumor and normal lung tissues." (PMID 41561767, 2025).
lung carcinoma (1 paper, 2025). "Future efforts should focus on validating MRPs in clinical cohorts and exploring WARS2-directed therapies as a novel avenue for precision medicine in lung cancer." (PMID 41561767, 2025).
lymphoma (1 paper, 2025). A malignant (clonal) proliferation of B- lymphocytes or T- lymphocytes which involves the lymph nodes, bone marrow and/or extranodal sites. "Through SMR analysis, we identified WARS2 and PTPN7 as key regulators of CD28−CD25++CD8br%CD8br immune cells and various lymphomas." (PMID 40360443, 2025).
male pattern baldness (1 paper, 2023). "The 2 prioritized genes on chromosome 1, TBX15 and WARS2, were associated with similar phenotypes, including male pattern baldness, white blood cells, measures of overall adiposity and its distribution, bone mineral density, and height." (PMID 37889180, 2023).
progressive myoclonus ataxia (1 paper, 2023). "Also, WARS2 mutations cause dopa-responsive early-onset parkinsonism and progressive myoclonus ataxia." (PMID 37055858, 2023).
Tremor (1 paper, 2023). An unintentional, oscillating to-and-fro muscle movement about a joint axis. "In summary, we report four patients with an early-onset tremor–parkinsonism syndrome due to biallelic WARS2 variants." (PMID 37107582, 2023). "The first cases with biallelic pathogenic variants in WARS2, described in 2017, had a predominant neurodevelopmental phenotype with developmental delay and intellectual disability, with only mild movement disorders such as tremor (OMIM: #617710)." (PMID 37107582, 2023). "In this study, we present four new patients with an early-onset tremor–parkinsonism syndrome, who were identified to have a WARS2-related disorder." (PMID 37107582, 2023).
movement disorder (4 papers, 2023 to 2025). Neurological conditions resulting in abnormal voluntary or involuntary movement, which may impact the speed, fluency, quality and ease of movement. "Biallelic variants in the mitochondrial form of the tryptophanyl-tRNA synthetases (WARS2) can cause a neurodevelopmental disorder with movement disorders including early-onset tremor–parkinsonism syndrome." (PMID 37107582, 2023). "WARS2 deficiency is phenotypically differentiated between epilepsy and movement disorder." (PMID 41179085, 2025). "Notably, movement disorders are often associated with metabolic diseases and have been described in conditions related to deficiencies in other aminoacyl-tRNA synthetases, including WARS2, CARS2, PARS2, RARS2, and AARS2." (PMID 41002930, 2025).
tumor (3 papers, 2017 to 2025). "Together, these results demonstrate that elevated metabolic risk, as indicated by high MRPs scores and WARS2 expression, is associated with reduced immune infiltration and an immunosuppressive tumor milieu—potentially underlying the poor prognosis observed in the MRP I subgroup." (PMID 41561767, 2025). "This tumor-specific and metabolically active signature supports WARS2 as a potential functional driver and therapeutic target in LUAD." (PMID 41561767, 2025). "We identified WARS2 as a key metabolic driver gene that is specifically enriched in cancer cells and functionally contributes to tumor growth and progression, as validated by both in vitro and in vivo experiments." (PMID 41561767, 2025). "To further elucidate how WARS2-positive cancer cells (CaWP) integrate into and influence the tumor microenvironment, we conducted a comprehensive pathway-level cell-cell communication analysis using the CellChat framework." (PMID 41561767, 2025). "Based on WARS2 expression status, we further stratified tumor-derived epithelial cells into WARS2-positive and WARS2-negative subpopulations for downstream comparative analysis." (PMID 41561767, 2025). "Within the tumor microenvironment, WARS2 expression was predominantly enriched in malignant epithelial (cancer) cells, with minor expression observed in fibroblasts and endothelial cells, and minimal expression across immune cell types." (PMID 41561767, 2025). "In vivo, xenograft models demonstrated that WARS2 knockdown markedly suppressed tumor growth, providing functional evidence that WARS2 may act as a pro-tumorigenic factor and a potential therapeutic target." (PMID 41561767, 2025). "The expression level of WARS2 was also consistent with this immunoevasive state, suggesting that WARS2 may be involved in reshaping the tumor immune microenvironment in LUAD." (PMID 41561767, 2025). "Immunohistochemistry confirmed efficient WARS2 knockdown in tumor tissues." (PMID 41561767, 2025). "Their prominent roles across multiple pro-tumorigenic communication pathways reinforce the hypothesis that WARS2 overexpression contributes to tumor progression through both cell-intrinsic metabolic rewiring and cell-extrinsic microenvironmental modulation." (PMID 41561767, 2025). "Finally, to determine whether WARS2 influences the tumor immune microenvironment, we analyzed immune cell populations in xenograft tumors by flow cytometry." (PMID 41561767, 2025). "Collectively, these data highlight the dual role of WARS2+ LUAD cancer cells as metabolically reprogrammed and communication-competent entities, capable of shaping both intracellular and intercellular tumor biology." (PMID 41561767, 2025). "Functional assays confirmed that WARS2 silencing impaired LUAD cell proliferation, invasion, and tumor growth." (PMID 41561767, 2025). "Collectively, these results confirm that WARS2 promotes LUAD progression by enhancing tumor cell proliferation and invasion, sustaining mitochondrial oxidative metabolism, and fostering an immune-suppressive microenvironment that favors tumor growth." (PMID 41561767, 2025).
cancer (1 paper, 2025). A tumor composed of atypical neoplastic, often pleomorphic cells that invade other tissues. "To further elucidate the functional roles of WARS2-positive cancer cells in LUAD, we performed AUCell-based pathway activity scoring and CellChat-mediated intercellular communication analysis." (PMID 41561767, 2025). "Differential expression analysis between WARS2+ and WARS2- cancer cells revealed widespread transcriptional reprogramming." (PMID 41561767, 2025). "Together, these results reveal that WARS2-positive cancer cells are not only metabolically and transcriptionally active but also occupy central positions in the LUAD intercellular signaling landscape." (PMID 41561767, 2025). "AUCell results showed that WARS2+ cancer cells (CaWP) exhibited elevated activity in multiple biological pathways compared to their WARS2- counterparts (CaWN)." (PMID 41561767, 2025). "Together, these results indicate that WARS2 is specifically overexpressed in LUAD cancer cells, where it marks a transcriptional state characterized by elevated biosynthetic and proliferative programs." (PMID 41561767, 2025). "Global signaling activity analysis revealed that CaWP cells exhibited markedly enhanced outgoing and incoming communication compared to WARS2-negative cancer cells (CaWN), suggesting that WARS2 expression is associated with a more interactive and functionally engaged cellular state." (PMID 41561767, 2025).
mitochondrial disease (1 paper, 2019). "In contrast, the p.Val278Gly substitution reported here has not been previously associated with mitochondrial disease, and its potential effect on WARS2 function is not immediately clear." (PMID 30920170, 2019). "Here we report two siblings with mitochondrial disease, due to compound heterozygous mutations in the mitochondrial tryptophanyl‐tRNA synthetase (WARS2) gene, presenting with severe neurological symptoms but normal mitochondrial function in skeletal muscle biopsies and cultured skin fibroblasts." (PMID 30920170, 2019).
WARS2 also shares sentences with these, for which no sentence is quoted: Intellectual disability (3 papers); metabolic disease (2); microcephaly (2); neurodevelopmental disorder (2); Ataxia (1); breast carcinoma (1); cardiac hypertrophy (1); central obesity (1); Failure to thrive (1); glioma (1); Hypoglycemia (1); lactic acidosis (1); Leigh syndrome (1); leukodystrophies (1); Leukoencephalopathy (1); liver cancer (1); optic atrophy (1); osteoporosis (1); ovarian failure (1); pantothenate kinase-associated neurodegeneration (1); peripheral vascular disease (1); retinitis pigmentosa (1); sensorineural hearing loss with (1); Stroke (1); type 2 diabetes (1).